HDAC1 (histone deacetylase 1)
Diseases named in the same sentence as HDAC1 in open-access papers (continued):
Sharing a sentence is not in itself a finding about the gene and the disease.
tumor (continued). "Selective inhibition of HDAC1 prevents tumor growth and metastasis in OS." (PMID 37240338, 2023). "The ΔNp63α/HDAC1/2 complex is also considered to be an important tumor maintenance factor." (PMID 36983561, 2023). "In addition, as a major transcriptional regulator of tumor cell response to hypoxia, HIF-1α can interact with histone deacetylase 1 (HDAC1) and cause immune dysfunction." (PMID 37921852, 2023). "We observed decreased tumor metastasis with either administration of ERK or HDAC1 inhibitor." (PMID 36647029, 2023). "Knock-down of HDAC1 or HDAC6 in vivo led to a more circumscribed less invasive tumor." (PMID 37528157, 2023). "Another study demonstrated that excess circulation of CXCL1 leads to a reduction in an extracellular matrix tumor-suppressor protein fibulin-1 through NF-κB/Histone Deacetylase 1 (HDAC1) epigenetic regulation, which facilitates the invasion and metastasis of CRC cells." (PMID 35954156, 2022). "Furthermore, an in vivo tumor metastasis model was developed to testify the effect of HDAC1 on tumor metastasis." (PMID 35395834, 2022). "Furthermore, TNF-α, VEGFA, and c-Myc were considered to serve important roles in tumorigenesis and tumor development, which can be regulated by HDAC1." (PMID 35053925, 2022). "According to some studies, high expression of HDAC1 in GC can be associated with age, Lauren’s classification, H. pylori infection, tumor size, lymphovascular invasion, lymph node metastasis (LNM), or even advanced tumor stages." (PMID 36358890, 2022). "We further aimed to demonstrate whether HDAC1 silencing could inhibit the tumorigenic capability of CC cells in an in vivo tumor formation model." (PMID 35395834, 2022). "Interestingly, we found that entinostat (target of HDAC1/HDAC3) acts as a tumor suppressor and a pro-apoptosis and cell cycle-blocking drug and acts on HCCLM3 and Huh-7 (concentrations of 0, 5, and 10 μM)." (PMID 36263167, 2022). "Furthermore, we demonstrate that pharmacological inhibition of the NANOG/HDAC1 axis with FK228 triggered anti–PD-1 therapy–mediated tumor regression and made immunologically “cold” tumors “hot” by initiating or reinvigorating the antitumor immunity cycle." (PMID 35104240, 2022). "HDAC1 can interact with NF-κB to promote tumor migration and invasion." (PMID 35756488, 2022). "Notably, inhibition of the NANOG/HDAC1 axis reversed the resistance to CTL-based immunotherapy in tumor cells and led to long-term control of the disease." (PMID 35104240, 2022). "Our results indicated that HDAC1 was highly expressed in tumor tissues." (PMID 36227941, 2022). "Here, we used a bottom-up proteomic approach to investigate the consequences of reduction of HDAC activity following the treatment with the HDACis Entinostat and Vorinostat or specific deletion of Hdac1 in cell lines derived from a transgenic NPM-ALK tumor mouse model." (PMID 35954222, 2022). "HDAC-2 expression was associated with tumor depth of invasion, while lack of correlation between HDAC-1 and -3 with any of the clinicopathological parameters was noted." (PMID 34441281, 2021). "Surprisingly, the expression of HDAC-1 in the normal hepatic tissue was linked with satellite nodules and multiple lesions, suggesting that HDAC-1 could be related to tumor spread." (PMID 34441281, 2021). "HDAC1 also affects tumor immunity by regulating the secretion of cytokines." (PMID 34880761, 2021). "In addition, researchers have demonstrated that inhibition of HDAC1/2 was able to suppress proliferation and induce tumor cell death in several HCC cell lines." (PMID 33783990, 2021). "This argues for a mixture of events explaining decreased tumor growth of HDAC1 and HDAC2 knockouts." (PMID 34654445, 2021).
tumor (continued). "In accordance with their results, the rest of the studies performed, also revealed the association of class I HDAC isoforms (HDAC-1, -2 and -3) with CRC, with their prevalence being linked to poor tumor differentiation, higher tumor grade and significantly reduced patient OS." (PMID 34441281, 2021). "Thus, it is necessary to better understand HDAC1 regulation to identify new strategies by which to specifically and effectively target aberrations in its expression or activity in different tumor types." (PMID 33976119, 2021). "In addition, increased expression of HDAC1 was related to the tumor aggressiveness and a poorer survival in patients with DLBCL." (PMID 34635181, 2021). "However, according to The Cancer Genome Atlas (TCGA) data-set, 4% of patients with ccRCC show upregulation of HDAC-1 and HDAC-6 mRNA and direct association with an advanced tumor stage in a, nevertheless, insignificant manner." (PMID 34441281, 2021). "HDAC1 is widely involved in various protein complexes’ catalytic processes, affecting the proliferation, metastasis, differentiation, infiltration, gene transcription, and other tumor cell processes." (PMID 34073721, 2021). "Susanna F. Greer found that downregulation of DNMT1 and HDAC1 expression in ovarian cancer cells induced by overexpression of RGS10 could inhibit tumor drug resistance." (PMID 34073721, 2021). "Although there is no report of HDAC1 regulating the proliferation or apoptosis of diabetic skin fibroblasts, HDAC inhibitors are often used as a treatment for cardiac fibrosis and tumours, which also shows that it is possible for Ski to regulate FoxO1 through HDAC1." (PMID 33349993, 2021). "Moderate or high HDAC1 expression was seen in 46% (80/179) of tumours." (PMID 34439236, 2021). "Studies have shown that 8a as an HDAC1 inhibitor may combine with different pathways to inhibit tumor cells’ growth." (PMID 34073721, 2021). "Knocking down HDAC1 in tumour cells partially contributed to G2/M phase arrest." (PMID 34395273, 2021). "A set of large-scale small molecule inhibitor screens and RNA-sequencing data lead us to hypothesize that the presence of intercellular crosstalk mediated by HDAC1 provokes the aggressive transformation of the edge cells for tumor initiation." (PMID 32938908, 2020). "The associations between HDAC1/HDAC2/HDAC3 and classical clinicopathological characteristics such as age, tumor size, histological grade, lymph node status, ER, PR, HER2, brain metastasis and molecular subtypes were analyzed by Spearman's rank‐correlation test and χ2 test." (PMID 32686908, 2020). "Furthermore, HDAC1 levels increased at advanced tumour stages (III/IV) in comparison with early stages (I/II)." (PMID 32429269, 2020). "Decreased expression of miR-34a and increased expression of HDAC1 are closely related to OC cell development, thus miR-34a may function as a tumor repressor by directly targeting and modulating HDAC1 expression in OC cells." (PMID 32336272, 2020). "Thus, HDAC1 has a dual role in tumorigenesis: oncosuppressive in the early stages and oncogenic in established tumor cells." (PMID 32585896, 2020). "The decreased expression of miR-34a and the increased expression of HDAC1 are closely related to OC cell development, and thus miR-34a may function as a tumor repressor by directly targeting and modulating HDAC1 expression in OC cells." (PMID 32336272, 2020). "Current literatures showed that FMNL1 incorporates with HDAC1 to facilitate tumor metastasis and that CXCR2 expression could be modulated by HDAC proteins." (PMID 33324547, 2020). "Together, these data support our working hypothesis that HDAC1/2 promotes lung tropism through regulation of the cells’ capabilities to escape the primary tumor site and extravasate to the lungs." (PMID 33035223, 2020).
tumor (continued). "The univariate results of Cox regression analysis showed that increased tumor size/histological grade/lymph node invasion/HDAC1/HDAC2/nuclear HDAC3/cytoplasmic HDAC3 were significantly associated with shorter overall survival, while positive ER or PR was associated with prolonged overall survival." (PMID 32686908, 2020). "Our current study demonstrated that the mRNA levels in cells and the protein levels in the supernatants of DNMT1, DNMT3a, DNMT3b, and HDAC1 increased with the increase of cell malignancy, which has provided a critical evidence in the search for tumor biomarkers from body fluid." (PMID 33383878, 2020). "Additionally, HDAC1 is revealed to be an EBV unique upstream regulator in the AGS-EBV tumors also confirming the shift to epigenetic regulation during tumor formation." (PMID 31584998, 2019). "Specifically, it has been determined that deacetylation of lysine 518 by HDAC1 is critical for the activation of GLI150 and that the HDAC1/2 inhibitor, vismodegib, could inhibit tumour growth in a mouse MB model." (PMID 31558698, 2019). "Determination of the expression pattern of HDAC class I‐IV family members in the tumor (2102EP) and endothelial cells (Ea.hy926) used in this study revealed that the class I family members HDAC1, HDAC2, and HDAC3 are the primarily expressed HDACs in both cell lines." (PMID 31583820, 2019). "In vivo, HDAC1 overexpression significantly increased doxorubicin resistance; while HDACs inhibitor Panobinostat markedly improved the inhibitory effect of doxorubicin on tumor growth." (PMID 31358016, 2019). "3MC upregulated the epithelial–mesenchymal transition (EMT) and tumor biomarkers; the models exhibited the reciprocal expression of histone deacetylase 1 (HDAC1) and RhoA, namely increased HDAC1 and decreased RhoA expression, through hypoxia-inducible-factor (HIF)- and AhR-dependent mechanisms." (PMID 30872677, 2019). "Furthermore, HDAC1 silencing by Panobinostat and/or lentivirus mediated RNA interference against HDAC1 effectively reduced doxorubicin resistance, resulting in the inhibition of tumor growth in AML bearing mice." (PMID 31358016, 2019). "As expected, HDAC1 silencing by Panobinostat and/or lentivirus mediated RNA interference against HDAC1 effectively reduced doxorubicin resistance, resulting in the inhibition of tumor growth in AML bearing mice." (PMID 31358016, 2019). "While this data is suggestive for high HDAC1 levels to correlate with sensitivity to HDACi treatment, more experimental data is required to determine whether a tumor-specific HDAC isoenzyme profile may predict the response to individual HDACi." (PMID 29651407, 2018). "Our data provide a possible framework for tumour-relevant functions of HDAC1 and HDAC2." (PMID 29472538, 2018). "Collectively, these data demonstrate that HDAC1/2 are regulated by the Hh signaling to support tumor cell proliferation and argue that a selective pharmacological targeting of these deacetylases may counteract SHH-MB growth." (PMID 28276480, 2017). "Gene expression profiling in this study identified critical AML tumor suppressor genes which may play important roles in mediating the combinatorial effects of HDAC1/2 inhibition with azacitidine." (PMID 28060870, 2017). "We observed that inhibiting HDAC1 could enhance the anti-tumor effects of statins both in vitro and in vivo." (PMID 28481295, 2017). "Tumor-suppressive miR-449A targets HDAC1 and induces growth arrest in PCa." (PMID 28651018, 2017). "Mice in the HDAC1-shRNA group and the NC group were killed 46 days after inoculation, with the mean tumor weight was markedly lower in the pLVTHM-HDAC1-shRNA group (0.27 ± 0.08 g) and compared to the pLVTHM-shRNA (negative control, NC) group (0.54 ± 0.16 g), respectively." (PMID 28624794, 2017). "In vivo data showed that knockdown of HDAC1 inhibited tumor growth in nude mice." (PMID 28624794, 2017).
tumor (continued). "Therefore, we performed conditional targeted deletion of Hdac1 and Hdac2 in Eμ-myc tumor cells using an in vivo transplantation approach." (PMID 27886239, 2016). "Eμ-myc mice with a single allele of Hdac2 and no Hdac1 (Hdac1Δ/Δ; Hdac2Δ/+), but not with a single allele of Hdac1 in absence of Hdac2 (Hdac1+/Δ; Hdac2Δ/Δ), exhibited delayed tumor development." (PMID 27886239, 2016). "Furthermore, a recent study also showed that ablation of both Hdac1 and Hdac2 decreases proliferation and induces apoptosis in Eμ-myc tumor cells." (PMID 27886239, 2016). "However, several recent studies reported opposing tumor-suppressive or tumor-promoting roles for Hdac1 and Hdac2." (PMID 27886239, 2016). "A previous report studying the effect of the HDACi depsipetide (FK228), which most potently inhibits all class I HDACs, demonstrated that the tumor most sensitive to depsipeptide treatment tested (a CNS-PNET) had the highest expression of HDAC2 relative to HDAC1, and 3-7." (PMID 25853389, 2015). "HDAC1/2 play redundant and essential roles in tumor cell survival." (PMID 25592494, 2015). "The role of CoREST1 in tumor/stroma interactions likely requires the known biochemical function of CoREST1 to promote recruitment and activity of associated histone modifying enzymes including LSD1 and/or HDAC1/2." (PMID 25793264, 2015). "A similar positive effect on cell proliferation by a single Hdac2 allele in the absence of HDAC1 in T cells was shown to favor tumor formation." (PMID 24449838, 2014). "In our study HDAC-1 was found to be of rough prognostic relevance in pTa and pT1 tumours." (PMID 24624923, 2014). "HDAC-1 and HDAC-2 were significantly associated with higher tumour grades." (PMID 24624923, 2014). "HDAC1/2 could directly mediate repressive functions of a number of well-characterized cellular oncogenes and tumor-suppressor genes, leading to aberrant gene expression." (PMID 24465727, 2014). "Transfection of CSCs with HDAC1-shRNA or pcDNA/miR-200b vector could obviously block tumor initiation in nude mice." (PMID 25279705, 2014). "Therefore, immunoprecipitation using specific antibodies determined the activity of individual HDAC family members and found that HDAC1, 2, 6 and 9 had elevated activity in tumor lysates compared to normal cerebellum." (PMID 23951168, 2013). "Furthermore, HDAC1 presence and activity are noted in the cytoplasm contributing to the activity and function of certain tumor promoting molecules such as HSP90." (PMID 24278104, 2013). "In addition, we found high expression of MBP-1 and HDAC1 in normal tissues and a statistically significant inverse correlation with ErbB2 expression in the paired tumor samples." (PMID 23421821, 2013). "In this study, using the mutagenesis approach we identified amino acid residue D346 as a unique intrinsic element of maspin that can be manipulated to redirect maspin from the cytoplasm to the nucleus, accompanied with increased inhibitory effect of maspin on HDAC1 in tumor cells." (PMID 24278104, 2013). "Consequently, HDAC1 siRNA significantly diminished VPA-mediated inhibition of tumor cell growth and activation of autophagic cell death." (PMID 23866964, 2013). "It remains unclear whether the translocation of maspin from the nucleus to the cytoplasm in tumor progression is an adaptation in response to the adverse HDAC1 activity in the cytoplasm." (PMID 24278104, 2013). "Furthermore, sustained suppression of HDAC1 attenuated in vitro colony formation and in vivo tumor growth in a mouse xenograft model." (PMID 22496786, 2012). "Interestingly, our data suggested that up-regulation of HDAC1 favored tumor cell metastasis, as evidenced by the fact that those tumors showing increased HDAC1 expression correlated with poor differentiation, older age, lymph node metastasis." (PMID 22455563, 2012). "Notably, CBP/p300 and HDAC1–3 exhibit opposing roles in tumor immunity." (PMID 40755753, 2025).
tumor (continued). "Also, the newly designed HDAC1/2/6 inhibitor SDFZ‐8 not only effectively upregulates PD‐L1 expression in tumor cells but also modulates lymphocyte expression of PD‐1 and PD‐L1, thereby alleviating the suppressive immune microenvironment and enhancing the therapeutic efficacy of anti‐PD‐L1 blockade." (PMID 41267925, 2025). "Therefore, inhibiting HDAC1 with Paromomycin may disrupt key signaling pathways controlled by HDAC1, potentially reducing tumor cell proliferation and invasiveness." (PMID 39723246, 2024). "Therefore, as a tumor-promoting factor, HDAC1 was chosen for further analysis." (PMID 38812060, 2024). "Because we recently discovered that HDAC1 promotes the tumorigenic properties and survival of GSCs, we questioned whether a brain-penetrant HDACi with higher affinity for HDAC1 would be effective in slowing tumor growth in vivo." (PMID 37991020, 2023). "Besides, HDAC1 knockdown in tumor cells could also impair G2/M transition and inhibits cell growth as evidenced by a reduction of mitotic cells." (PMID 35062876, 2022). "We next assessed whether HDAC1 inhibition could switch the immune phenotype in the TME from an immune-refractory to an immune-stimulatory feature by reinvigorating the antitumor immunity cycle in NANOGhi-refractory tumor cells." (PMID 35104240, 2022). "Thus, we provide proof-of-concept evidence that HDAC1 inhibition by pharmacological interventions could suppress tumor progression and sensitize NANOGhi-refractory tumors to anti–PD-1 therapy." (PMID 35104240, 2022). "C18-ceramide production by CerS1 is inhibited in HNSCC through transcriptional repression via histone deacetylase 1 (HDAC1)-dependent inhibition of Sp1 at the promoter, and post-transcriptionally by miR574-5p that induces translation of a CerS1 isoform 2 splice variant common in HNSCC tumor tissues." (PMID 34069611, 2021). "Combination therapy of HDACi together with PRC2 inhibitors like the EED inihibitor A-395, that interfere with chromatin binding of the PRC2/HDAC1/2 complex, significantly block tumor growth of EwS in a xenograft mouse model and could be an interesting new treatment option for this malignant disease." (PMID 34654445, 2021). "Furthermore, downregulation of NEAT1 could reduce NEAT1 level (P<0.05) and the expression of p-AKT and HDAC1 (P<0.05) in tumor tissues, while increase miR-524-5p expression (P<0.05) and Ac-PTEN level (P<0.05)." (PMID 34837887, 2021). "Similarly, in breast cancer, higher HDAC1 expression correlated with more aggressive tumours." (PMID 34439236, 2021). "The high-intensity staining in a large proportion of these tumor samples (71.4% for HDAC1 and 92.9% for HDAC2) suggests that HDACs are also relevant in the context of cisplatin-resistant phenotype, thus indicating that targeting with HDACis may be an effective therapy." (PMID 33050470, 2020). "In addition, a more recent study has shown that HDAC1 may play an important role in tumor formation, phosphorylating a specific location of HDAC1 by CK2 to regulate its activity and cause tumors." (PMID 33114312, 2020). "The authors demonstrated that HDAC1 played a central in the reversal of carcinoma immune escape through the induction of ER stress, resulting in the activation of the unfolded response, subsequently leading to immunogenic modulation and increased tumor sensitivity to T-cell mediated lysis." (PMID 29651407, 2018).